ZBTB7B (zinc finger and BTB domain containing 7B)
Diseases named in the same sentence as ZBTB7B in open-access papers:
ZBTB7B is named in the same sentence as 39 diseases in open-access papers, as found by Europe PMC text mining. Sharing a sentence is not in itself a finding about the gene and the disease. The quoted sentences say what the papers report.
gastric cancer (4 papers, 2022 to 2025). A primary or metastatic malignant neoplasm involving the stomach. "Previous studies have linked low ZBTB7B expression with a high risk and increased immune cell infiltration in gastric cancer patients." (PMID 40377813, 2025). "This study aimed to investigate the effect of Zinc finger and BTB domain containing 7B (Zbtb7b, Alias ThPOK) on T cell activation after coculture with gastric cancer cells." (PMID 35379170, 2022).
breast carcinoma (3 papers, 2025 to 2026). "As a result, we identified T-helper-inducing Poxviruses and Zinc-finger (POZ)/Krüppel-like factor (ThPOK, ZBTB7B), a CD4+ cell lineage commitment factor, as a breast cancer master regulator that is recurrently associated with a SE." (PMID 40235471, 2025). "In this study we employed a multi-omic approach that integrates SE profiling and transcriptomic analysis of 17 normal mammary and breast cancer cell lines with a breast cancer-specific gene regulatory network, revealing ThPOK/ZBTB7B as a subtype-specific master regulator in breast cancer." (PMID 41231242, 2025). "Additionally, we observed that deletions of the ZBTB7B gene correlated with shorter time to metastasis (Metastatic Breast Cancer Project data)." (PMID 41231242, 2025).
breast invasive carcinoma (3 papers, 2020 to 2025). "IRF5, MAP2K2 (MEK2), and ZBTB7B were significantly overexpressed (p < 0.05) in invasive breast cancer blood samples but not in DCIS blood samples." (PMID 37445737, 2023). "Similarly, the motifs CGR (breast invasive carcinoma), CACAAR (glioblastoma multiforme), ATGWTG (lung squamous cell carcinoma), CGWCCGAA (prostate adenocarcinoma) show exclusive affinity for YY2, RUNX1, ATF4 and ZBTB7B, respectively." (PMID 32015379, 2020).
colonic inflammation (3 papers, 2022 to 2023). "Moreover, the underlying molecular mechanism related to Zbtb7b in the pathogenesis of UC was explored using the dextran sodium sulfate (DSS)-induced colitis model." (PMID 35761286, 2022). "It was shown that the expression of Zbtb7b at the mRNA level was significantly up-regulated in DSS-induced colitis (P < 0.0001)." (PMID 35761286, 2022). "Inhibition or deletion of Zbtb7b will mediate the reduction of the intestinal immune response, resulting in less colitis." (PMID 35761286, 2022). "In addition, WB and IHC showed that the expression of ZBTB7B at the protein level was significantly increased in DSS-induced colitis (P = 0.0045, P = 0.0004)." (PMID 35761286, 2022). "Finally, we found the hypo-methylation of Zbtb7b through the GEO database and preliminary verified it in the mouse model of colitis." (PMID 35761286, 2022). "To further explore the underlying molecular mechanism related to Zbtb7b in the pathogenesis of UC, we established a DSS-induced colitis model in C57BL/6 mice by administering 3% DSS for 7 days in the drinking water, and the dynamic process of colitis was monitored." (PMID 35761286, 2022). "DNA hypo-methylation of gene Zbtb7b, referred to as the Th-inducing POZ-Kruppel factor (Th-POK), could activate the maturation of CD4+ T cells and repress the differentiation of double-positive T cells, leading to the secretion of inflammatory cytokines and thus causing colonic inflammation in UC." (PMID 38169708, 2023). "In summary, we demonstrated that Zbtb7b was demethylated and up-regulated in the UC and DSS-induced colitis model." (PMID 35761286, 2022). "In the present study, we also found that Zbtb7b was significantly up-regulated in colonic tissue samples from UC patients and the DSS-induced colitis model." (PMID 35761286, 2022). "Interestingly, our previous research has revealed that Zbtb7b is significantly upregulated in colonic tissue samples from UC patients and the DSS-induced colitis model." (PMID 37653406, 2023). "Mechanistically, PELNs enhanced the growth of Lactobacillus reuteri and increased indole derivatives levels, which led to the downregulation of Zbtb7b expression and subsequently induced the differentiation of double-positive CD4+CD8+T cells (DP CD4+CD8+ T cells) in mice with colitis." (PMID 37653406, 2023). "In our present study, oral administration of PELNs significantly increased the levels of indole derivatives, effectively decreased the expression of Zbtb7b, and prominently facilitated the differentiation of DP CD4+CD8+ T cells in colonic tissues of mice with DSS-induced colitis." (PMID 37653406, 2023). "Epigenetic DNA hypo-methylation of Zbtb7b activated the maturation of CD4+T cells and repressed the differentiation of DP CD4+CD8+ T cells, resulting in the production of inflammatory cytokines and colonic inflammation in UC." (PMID 35761286, 2022). "Therefore, we considered that the over-expression of Zbtb7b promoted the differentiation of CD4+T cells, subsequently contributing to the production of inflammatory cytokines in the DSS-induced colitis model." (PMID 35761286, 2022). "Importantly, the PELNs-Lactobacillus reuteri-indole-derivatives axis played a crucial role in downregulating the expression of Zbtb7b in conventional CD4+ T cells, resulting in the reprogramming of conventional CD4+ T cells into DP CD4+CD8+ T cells and subsequently alleviating colitis in mice." (PMID 37653406, 2023). "We further verified that demethylated Zbtb7b activated the maturation of CD4+T cells and repressed the differentiation of DP CD4+CD8+ T cells, resulting in the production of inflammatory cytokines and colonic inflammation in the UC and DSS-induced colitis model." (PMID 35761286, 2022). "Furthermore, we validated that Zbtb7b activated CD4+T cells and repressed CD4+ CD8+T cells in the inflamed colonic tissues of UC, which contributed to the colonic inflammation in the dextran sodium sulfate (DSS)-induced colitis model." (PMID 35761286, 2022).
colonic inflammation (continued). "Therefore, over-expression of Zbtb7b might repress the differentiation of DP CD4+CD8+ T cells and then increase the production of inflammatory cytokines, such as TNF-α, IL-17, and IFN-γ, in the DSS-induced colitis model." (PMID 35761286, 2022). "Moreover, over-expression of Zbtb7b activated the maturation of CD4+T cells and repressed the differentiation of DP CD4+CD8+ T cells, which contributed to the production of inflammatory cytokines, such as TNF-α, IL-17, and IFN-γ, in the DSS-induced colitis model." (PMID 35761286, 2022). "When Zbtb7b is absent, the activated CD4+ IELs lose their inflammatory function, resulting in the inability to induce colitis." (PMID 35761286, 2022). "In addition, we initially explored the relationship between demethylated Zbtb7b and T cell immunity in the DSS-induced colitis model, while those findings were not further verified in vitro." (PMID 35761286, 2022).
glioblastoma (2 papers, 2020 to 2023). The most malignant astrocytic tumor (WHO grade IV). "Interestingly, the deletion of the H3K27ac-preferred SE regions of BCL2 and ZBTB7B neither reduced the expression of their target genes nor the glioblastoma stem-like properties." (PMID 37759202, 2023).
hepatocellular carcinoma (2 papers, 2024 to 2025). A malignant tumor that arises from hepatocytes. "To determine to which extent ZBTB7B might be associated with human liver cancer phenotypes, we queried the Cancer Genome Atlas hepatocellular carcinoma (TCGA_LIHC) dataset." (PMID 38225233, 2024).
lymphoma (2 papers, 2016 to 2022). A malignant (clonal) proliferation of B- lymphocytes or T- lymphocytes which involves the lymph nodes, bone marrow and/or extranodal sites. "ZBTB7B is a known oncogene in lymphoma and is thought to promote cell transformation and oncogenesis by suppressing apoptosis in cells with Ras and Myc activation." (PMID 27223260, 2016).
angioimmunoblastic T-cell lymphoma (1 paper, 2021). A mature T-cell non-Hodgkin lymphoma, characterized by systemic disease and a polymorphous infiltrate involving lymph nodes and extranodal sites. "Moreover, a great proportion of human angioimmunoblastic T-cell lymphoma (AITL) express ZBTB7B, which appears to correlate with poor prognosis." (PMID 34349770, 2021).
breast tumors (1 paper, 2025). "The ThPOK/ZBTB7B gene is associated with a SE in cells derived from different breast tumor subtypes, a feature that distinguishes key transcriptional regulators in cancer." (PMID 41231242, 2025).
cerebral malaria (1 paper, 2022). A sequestration of Plasmodium falciparum in the brain, which can cause coma and/or seizures. "A third ENU-derived mutation, impacting the ZBTB7B (ThPOK) zinc finger transcription factor, was identified that caused protection against cerebral malaria caused by P. berghei ANKA." (PMID 35646724, 2022).
cervical cancer (1 paper, 2021). A primary or metastatic malignant neoplasm involving the cervix. "Zinc-finger and BTB domain-containing 7B (ZBTB7C), a member of the ZBTB transcription factor family, has reduced or absent expression in most cervical cancer cell lines and has been proven to inhibit the proliferation of cervical cancer cells." (PMID 33946045, 2021).
colon cancer (1 paper, 2024). "Statistical analysis revealed that in non-small cell lung cancer (NSCLC) and colon cancer, ALDH1A1 and ZBTB7B were positively correlated with CD274 mRNA expression." (PMID 39107297, 2024).
glioma (1 paper, 2026). A benign or malignant brain and spinal cord tumor that arises from glial cells (astrocytes, oligodendrocytes, ependymal cells). "Clinical validation through multiplex immunofluorescence staining on a tissue microarray of 129 glioma samples revealed a progressive loss of ZBTB7B protein expression across WHO grades II to IV, inversely correlating with tumor malignancy." (PMID 41294275, 2026). "Therefore, we propose ZBTB7B reactivation as a novel therapeutic strategy for glioma." (PMID 41294275, 2026).
liver cancer (1 paper, 2024). An epithelial or non-epithelial malignant neoplasm that arises from the liver. "Integrative multi-omics analyses identify c-Jun as the core signaling node in ZBTB7B-deficient liver cancer initiation." (PMID 38225233, 2024). "c-Jun is a direct target of ZBTB7B essential to accelerated liver cancer initiation in ZBTB7B-deficient livers." (PMID 38225233, 2024). "As c-Jun was identified as a core signaling node in Akt/N-Ras-induced ZBTB7B-deficient liver cancer initiation, we next sought to investigate whether ZBTB7B deficiency accelerates liver cancer initiation through c-Jun." (PMID 38225233, 2024). "As ZBTB7B deficiency primed the livers to the fetal-like state and accelerated Akt/N-Ras-induced liver cancer initiation, we next sought to investigate whether ZBTB7B-deficient hepatocytes would be susceptible to single oncogene-induced liver cancer." (PMID 38225233, 2024). "PPI sub-network of DEGs and DEPs synergistically regulated by ZBTB7B and Akt/N-Ras oncogens (clusters 2, 4, 5, and 6) further revealed c-Jun as the central signaling node in accelerated liver cancer initiation in the Zbtb7bΔli livers." (PMID 38225233, 2024). "ZBTB7B bound to the promoters of known ZBTB7B targets genes, e.g., Irs1, as well as genes important in liver cancer, including Jun, Akt1, Ccnd1, and Mki67." (PMID 38225233, 2024). "ZBTB7B activity was significantly lower in all stage/grade liver cancers, compared to the adjacent normal tissues." (PMID 38225233, 2024). "A comparison of liver cancers at different stages and grades revealed that advanced liver cancer only had a moderate further decrease of ZBTB7B activity." (PMID 38225233, 2024). "Ablation of Zbtb7b in hepatocytes significantly accelerated Akt/N-Ras-induced liver cancer development with median survival of 27.5 days." (PMID 38225233, 2024). "Comparison of paired tumor samples and adjacent normal liver tissues further supported that ZBTB7B activity was downregulated in the liver cancer." (PMID 38225233, 2024). "To evaluate the functions of ZBTB7B in hepatocarcinogenesis, we performed hepatocyte-specific ZBTB7B knockout in hydrodynamic oncogene transfer-induced mouse liver cancer models." (PMID 38225233, 2024). "DN-c-Jun expression completely abolished Akt-induced liver cancer development in the Zbtb7bΔli livers, suggesting c-Jun is downstream of ZBTB7B mediating hepatocyte transformation and liver cancer development." (PMID 38225233, 2024). "In a second cohort of 244 liver cancer patients, ZBTB7B activity was similarly lower in the liver cancers compared to the adjacent normal tissues, but comparable among different stages." (PMID 38225233, 2024). "We next sought to investigate whether ZBTB7B suppresses liver cancer development by blocking c-Jun function, in addition to regulating c-Jun expression." (PMID 38225233, 2024). "It is yet unknown whether ZBTB7B regulates hepatocyte differentiation, liver functions, and liver cancer development." (PMID 38225233, 2024).
steatosis (1 paper, 2024). Increased lipid within the cytoplasm of cells. "Zbtb7b depletion accelerated the MASLD process by increasing the plasma and liver TG and cholesterol contents and leading to hepatic steatosis and inflammation upon HFD feeding." (PMID 39714087, 2024).
cancer (10 papers, 2013 to 2025). A tumor composed of atypical neoplastic, often pleomorphic cells that invade other tissues. "Functional enrichment analysis of ZBTB7B target genes suggested that ZBTB7B played a more prominent role in pathways in metabolism and cancer." (PMID 38225233, 2024). "Upon ZBTB7B deletion, additional c-Jun binding peaks were detected in genes involved in regulating metabolism and cancer." (PMID 38225233, 2024). "Prior experimental results have demonstrated that Aldh1a1, as a crucial upstream molecule of Zbtb7b, contributes to the immune evasion of cancer cells." (PMID 39107297, 2024).
tumor (10 papers, 2011 to 2026). "Ectopic ZBTB7B expression alleviated tumor burden with reduced tumor numbers, tumor area, and proliferative hepatocyte numbers." (PMID 38225233, 2024). "As deficiency of ZBTB7B, an adult liver-enriched cell fate regulator, in hepatocytes primed the livers to a fetal-like state and its expression was downregulated in the tumors, we next sought to investigate whether hepatocyte ZBTB7B would function as a tumor suppressor in regulating HCC development." (PMID 38225233, 2024). "In contrast to more preneoplastic nodules at 2 weeks and more tumors and proliferative hepatocytes at 4 weeks after active c-Jun expression, simultaneous overexpression of ZBTB7B completely abolished the tumor-promoting effects of active c-Jun." (PMID 38225233, 2024). "ZBTB7B exerts tumor-suppressive functions by directly regulating c-Jun expression and competing with c-Jun for chromatin binding." (PMID 38225233, 2024). "ZBTB7B overexpression reduced the numbers of preneoplastic nodules, tumor numbers, tumor area, and Ki67+ proliferative hepatocyte numbers to the levels of vector control." (PMID 38225233, 2024). "Specifically, ALDH1A1 upregulates ZBTB7B in tumor cells, subsequently promoting the upregulation of LDHA." (PMID 39107297, 2024). "ZBTB7B exerts tumor-suppressive functions by directly regulating c-Jun expression and function." (PMID 38225233, 2024). "Ectopic ZBTB7B expression attenuates the tumor-promoting functions of c-Jun." (PMID 38225233, 2024). "Finally, after conducting additional verification of patient tissue and clinical data, we have confirmed the potential translational value of targeting ALDH1A1 and ZBTB7B for tumor immunotherapy." (PMID 39107297, 2024). "Additionally, we identified that ALDH1A1 exacerbates the immune evasion characteristics of tumor cells by modulating the ZBTB7B-glycolysis regulatory pathway." (PMID 39107297, 2024). "The protein expression of ALDH1A1, ZBTB7B, and PD-L1 was evaluated in tumor biopsy tissue." (PMID 39107297, 2024). "ALDH1A1, through the ZBTB7B-glycolysis pathway, instigates the excessive accumulation of lactic acid in the tumor microenvironment, culminating in the diminution of anti-tumor immune cell infiltration in the tumor tissue and, consequently, amplifying tumor immune escape." (PMID 39107297, 2024). "RNA-seq re-validation confirmed that ZBTB7B knockdown resulted in reduced expression levels of LDHA and PD-L1 in tumor cells, establishing LDHA and PD-L1 as downstream effectors of ZBTB7B." (PMID 39107297, 2024). "In this study, we elucidate that ZBTB7B, a member of the ZBTB family, functions as a transcriptional regulator of LDHA, the key rate-limiting enzyme controlling lactate production in tumor cells." (PMID 39107297, 2024). "These preclinical results provide further validation of the potential benefits of targeting the ALDH1A1-ZBTB7B axis in tumor patients with high expression of ALDH1A1 and ZBTB7B." (PMID 39107297, 2024). "Notably, we identified EOCRC tumor-specific splicing of ZBTB7B (Th-POK), a zinc finger transcription factor which controls T-cell differentiation into CD4+ or CD8+ T-cells, and MAP3K8 (TPL2), a driver of oncogenic inflammation, though the biological function of these splice variants remains unknown." (PMID 38680862, 2024). "Here, DNA binding activity at gene specific promoters of Xlr, Nr2f1, Zbtb7b, Sprr2i, Ffg18 and ERBB3 was observed with nuclear extracts of transgenic and tumor bearing mice but the overall activity varied considerably with no obvious trend." (PMID 21464922, 2011). "ZBTB7B, a transcription factor of the rate-limiting enzyme LDHA involved in lactate production in glycolysis, emerges as a critical gene contributing to the failure of tumor cell immunotherapy." (PMID 39107297, 2024).
infection (3 papers, 2022 to 2025). The state of being infected such as from the introduction of a foreign agent such as serum, vaccine, antigenic substance or organism. "The most significant longitudinal changes in PBMC DNAme throughout infection were at the CpG sites associated with the SPRED2 (hypomethylation) and ZBTB7B, also known as ThPOK (hypermethylation) genes." (PMID 40662355, 2025).
bacterial infection (1 paper, 2022). "The expressions of Zbtb7b and RUNX3 restrict each other, affect the response of CD4+ T cells, and impair intestinal inflammatory immunity and the probability of exogenous bacterial infection." (PMID 35761286, 2022).
ZBTB7B also shares sentences with these, for which no sentence is quoted: acute lymphoblastic leukemia (1 paper); colorectal (1); colorectal cancer (1); cytomegalovirus infection (1); Down syndrome (1); Ewing sarcoma (1); Hepatic steatosis (1); inflammation (1); Intellectual disability (1); Intestinal Infection (1); invasive ductal carcinoma (1); lung squamous cell carcinoma (1); melanoma (1); non-small cell lung carcinoma (1); prostate adenocarcinoma (1); radiation pneumonitis (1); T-cell acute lymphoblastic leukemia (1); thymic lymphomas (1); ulcerative colitis (1); viral infection (1).